STAT3 (signal transducer and activator of transcription 3)
Diseases named in the same sentence as STAT3 in open-access papers (continued):
Sharing a sentence is not in itself a finding about the gene and the disease.
tumor (continued). "Previous studies have shown that IL-6 can activate STAT-3, the major downstream signaling pathway for IL-6, and it plays a role in the maintenance of CRC cell survival and tumor initiation." (PMID 36466926, 2022). "Therefore, inhibition of tumor myeloid cells through STAT3 targeting by mc-1Stat3 could explain why the relevant regression of lung metastasis surface induced by mc-1Stat3 treatment contrasts with the weak reduction of 4T1 TNBC cancer cell migration we observed in vitro." (PMID 35847174, 2022). "In TME, immune cells MDSC can achieve tumor suppression by regulating TAM, and down-regulate STAT3, which is related to inflammation." (PMID 36686745, 2022). "At the molecular level, CCL21/CCR7 can promote lymphatic metastasis of tumours via activating the ERK1/2 22 and JAK2/STAT3 signalling pathways." (PMID 35280672, 2022). "In vivo, β-Ele and cisplatin synergistically suppressed the tumor growth and induced apoptosis, and down-regulated the expression of p-JAK2 and p-STAT3." (PMID 35909161, 2022). "LLL12, prevents IL-6-induced STAT3 phosphorylation at Y705, and demonstrates efficacy in vivo in a TNBC MFP mouse model with a concomitant reduction in tumor volume and pSTAT3 expression." (PMID 35371975, 2022). "In the greatest number of tumors, STAT4 was correlated with tumor growth, then STAT1, STAT3, STAT6, STAT5B, STAT2, and STAT5A." (PMID 36176415, 2022). "Silibinin inhibits signal transducer and activator of transcription 3 (STAT3), which is expressed by astrocytes that are interacting with tumor cells." (PMID 35505937, 2022). "Activated STATs (STAT3 and STAT5) have been found to regulate the expression of VEGF by directly binding to its promoter, thereby strengthening VEGF expression and tumor angiogenesis." (PMID 35401182, 2022). "To further validate the relevance of IL-6/STAT3 axis in the control of SMG1 expression and thus of the NMD activity, we used different tumor-cells expressing the NMD luciferase reporter plasmid cultured in the presence of hyper-IL6." (PMID 36443756, 2022). "Meanwhile, sorafenib suppresses tumor angiogenesis and proliferation by inhibiting multikinases such as the serine/threonine kinase family (e.g., Raf-1, PI3K/Akt, ERK1/2, and STAT3) and the receptor tyrosine kinase family (e.g., FGFR, VEGFR, and PDGFR)." (PMID 35770048, 2022). "Further mechanistic research indicated that baicalein and baicalin decreased STAT3 activity, down-regulated IFN-γ-induced PD-L1 expression, and subsequently restored T cell sensitivity to eliminate tumor cells." (PMID 36232344, 2022). "FAP also induces inflammatory CAFs by STAT3 activation leading to increased expression of CCL2, which promotes the tumor recruitment of myeloid-derived suppressor cells (MDSCs) and immunosuppression." (PMID 35222418, 2022). "In NPM1–TYK2 tumor tissue, high fusion kinase activity resulted in the upregulation of phosphorylated STAT1, STAT3, and STAT5." (PMID 35042970, 2022). "Among them, IL23 is believed to involve in inflammatory responses which preferentially activate STAT-3 pathway; STAT-3 has many tumor-promoting functions, such as promoting tumor survival, proliferation, invasion and angiogenesis." (PMID 35903544, 2022). "Studies have shown that extracellular matrix remodeling can regulate pathways such as integrin-mediated signaling, TGF-β/STAT3 signaling, and DDR1/STAT3 signaling to activate multiple signaling pathways to promote tumor survival and proliferation." (PMID 36424540, 2022). "In the tumor tissues following oe-LINC00858 + sh-PCNP treatment, RAD21 expression was not altered while PCNP expression and phosphorylation levels of STAT3 and STAT5 were decreased in those following oe-LINC00858 + sh-NC treatment." (PMID 35468892, 2022). "Here, we uncover a critical role of the PIKE-A/STAT3/FTO/SDHA axis in promoting mitochondrial metabolism, which was a benefit for tumor growth." (PMID 36232604, 2022).
tumor (continued). "Specifically, in GBM stem cells, AKT phosphorylates EZH2, and then it methylates STAT3 leading to enhanced STAT3 activity, which promotes GSC self-renewal and tumor malignancy." (PMID 35197928, 2022). "Taken together, autocrine HGFL-RON signaling in tumor cells leads to the activation of pathways (including MAPK, and partially Akt/Stat3), which support macrophage migration." (PMID 35626096, 2022). "miR-181b activates STAT3, promoting the Warburg effect in CRC cells and CRC xenograft growth in mice, and does that by inhibiting PIAS3 expression, as the Warburg effect and tumor growth are reversed with PIAS3 overexpression." (PMID 35887358, 2022). "During tumor development the number of MDSC in the TME increases, where they suppress anti-tumor cytotoxic responses via activation of STAT3." (PMID 36555392, 2022). "Generally, STAT1 and STAT3 are considered to have opposite effects, with STAT1 being considered a tumor suppressor and STAT3 an oncogene." (PMID 35806366, 2022). "Collectively, we define a critical role of LXN/JAK1/STAT3 signal in macrophage and highlights the potential role of LXN in tumor immune-escape by regulating macrophage polarization, as well as the expression of immune checkpoint PD-L2." (PMID 36323670, 2022). "Small interfering RNAs targeting STAT3 can reduce the GSC population in vitro and tumor growth in vivo." (PMID 35954407, 2022). "At the protein level, the upregulation of p-STAT3, TAP1, β2M (MHC-I-related protein) and PD-L1 were also observed in MC38 tumor tissues." (PMID 34976211, 2022). "DYRK1A was found to be coexpressed with several STAT3 target genes, including zinc finger E-box-binding homeobox 1, VEGFA and heat shock protein 90, in clinical tumour samples from patients with HCC." (PMID 35655269, 2022). "In lung adenocarcinoma cells, highly expressed membrane progesterone receptor α (mPR) activation enhances JAK/STAT3 signaling, increases VEGF secretion in the tumor microenvironment, and promotes tumor blood vessel formation." (PMID 35559037, 2022). "After removing the tumour, we performed western blotting and immunohistochemical experiments on the tumours of the mice to test the expression of STAT3 and PCNA, which represents tumour proliferation." (PMID 35517401, 2022). "Strikingly, Vav:Cre-Phd2fl/fl mice displayed a tumor-promoting phenotype upon AOM/DSS treatment with increased tumoral activity of STAT3 and ERK1/2, confirming the notion that these 2 pathways at least contribute to PHD2-mediated CAC tumor development." (PMID 36509284, 2022). "Similarly, adoptive transfer of intrinsically activated STAT3-expressing B lymphocytes into implanted Rag1−/− mice, lacking mature T or B cells, contributes to tumor growth and progression, whereas adding STAT3-deficient B cells to the TME results in reduced tumor development." (PMID 35759090, 2022). "Tumor vessels in ABC samples appeared lined by endothelial cells expressing both FVIII and STAT3 signals, while in GCB samples, only few vessels co-expressed FVIII and STAT3." (PMID 35328127, 2022). "Signal transduction and activator of transcription 3 (STAT3) is a core member of the STAT family, which is considered as a key regulator of cancer and involved in tumor invasion, metastasis, angiogenesis, and immune escape." (PMID 35475457, 2022). "Immunohistochemical staining showed that treatment with AdipoRon significantly decreased the levels of p-p65 and p-STAT3, further validating the inhibitory effect of adiponectin, likely through the NF-kB and STAT3 pathways, on NPC tumor metastasis." (PMID 36361525, 2022). "Coincidentally, it has also been shown that tumor-derived GM-CSF, lactate, and extracellular vesicles can induce PD-L1 expression in neutrophils through activating JAK and STAT3 signaling pathway." (PMID 36369287, 2022).
tumor (continued). "Our findings implied that miR-577 targeted and inactivated STAT3, and the use of the STAT3 agonist colivelin restrained the inhibition of miR-577 on NSCLC cells, including partially recovering tumor cell proliferation, migration, invasion and EMT." (PMID 35475457, 2022). "The signal transducer and activator of transcription 3 (STAT3) belongs to the STAT family and is an important transcription factor involved in inflammation and tumor progression." (PMID 36230941, 2022). "At the same time, the platform released sunitinib and active oxygen to induce apoptosis and inhibit tumor angiogenesis, with increased expression of cleaved PARP and decreased levels of VEGFA, HIF-1α, survivin, and p-STAT3." (PMID 35784750, 2022). "Although BNIP3 is a potential target of ULK1, decreased BNIP3 protein levels in STAT3‐KO and mutant expressing cells indicate that BNIP3 is degraded by ULK1‐dependent autophagy, a mechanism found to decrease BNIP3 protein levels in tumour cells." (PMID 35670018, 2022). "Throughout the TME (adjacent brain/infiltrating edge, tumor, and regions of necrosis), CD3+p-STAT3– T cell/CD163+pSTAT3– macrophage clusters were significantly more common in brain metastases (P = 0.024, P = 0.01, and P = 0.045, respectively)." (PMID 35316217, 2022). "Previous studies reported that sorafenib as well as its derivative sc-1 were capable of downregulating the activation of STAT3 and ERK pathways and reducing tumor volumes." (PMID 36012610, 2022). "PM-73G, phosphopeptide molecular mimic that synthesized to target the SH2 domain of STAT3, reduced MVD and VEGF levels by the suppression of p-STAT3 (Tyr705) in mice bearing MDA-MB-468 tumor." (PMID 35784750, 2022). "Previous evidence from preclinical models and tumor tissues support that TLR4 and STAT3 signaling pathways cooperate on cancer cells to promote EMT, stemness, tumor growth, and immunosuppression." (PMID 35205801, 2022). "EGF can induce STAT3 activation and block the interaction between STAT3 and EGFR, which can inhibit tumor growth." (PMID 35547655, 2022). "The IL-6/JAK2/STAT3 pathway and CXCL12/CXCR4 interactions between tumor cells and CAFs were enriched." (PMID 35784460, 2022). "Overexpression of lncRNA PVT1 activates the STAT3/VEGFA pathway, sparks the angiogenesis in tumor cells, and vigorously boosts GC progression in vitro and in vivo." (PMID 35012438, 2022). "We used a functional proteomics tumor pathway technology platform and multiple HCC cell lines to investigate the effects of acacetin (ACN) on STAT3 activation, protein kinases, phosphatases, products of STAT3-regulated genes, and apoptosis." (PMID 36080130, 2022). "The addition of erlotinib or si-EGFR to the medium reduced the level of p-STAT3; therefore, we conclude that NNMT promotes tumor proliferation and metastasis through the EGFR-STAT3 pathway." (PMID 35851575, 2022). "Taken together, this suggests that EREG signaling at least in part contributes to the activation of the oncogenic STAT3 and ERK1/2 signaling pathways in Phd2+/– tumor cells in CAC." (PMID 36509284, 2022). "For all these processes induced by MFG-E8, multiple signaling pathways have been identified as important in tumor progression, such as the αvβ3/5 integrin, the PI3K/Akt, and the STAT3/SOCS3 pathways." (PMID 35681775, 2022). "The combination of radiation and STAT3 blockade with WP1066 in preclinical models markedly influenced the TME by inducing DC and T-cell infiltration within the tumor." (PMID 36011015, 2022). "STAT3-/- hosts had increased IFNγ production by CD8+ T cells, tumor infiltration, and decreased number of Tregs." (PMID 35270020, 2022). "Through regulating the JAK2/STAT3/FOXM1 axis, in vivo tumor xenograft assays further demonstrated that knockdown of AGK inhibited tumor development and decreased resistance to paclitaxel." (PMID 36313702, 2022).
tumor (continued). "In the previous study, we have identified a critical role of the PIKE-A/STAT3/G6PD axis in promoting biosynthesis and anti-oxidant defense, which benefits tumor growth and suppression of cellular senescence." (PMID 36232604, 2022). "EGFR is a receptor tyrosine kinase, which can act as a regulator of tumor immune monitoring, activate the JAK/STAT3 signaling pathway, and promote the expression of PD-L1." (PMID 35707465, 2022). "We demonstrated that the expression of both STAT3 and SOCS3 was up-regulated in DMS114 tumor cells pre-incubated with the tumor-activated SC-conditioned medium." (PMID 36551618, 2022). "Together, RCC-derived exosomes facilitate the development of tumor through inducing macrophage polarization via transferring lncARSR, suggesting that RCC-derived exosomes, lncARSR and STAT3 are the potential therapeutic targets for treatment of RCC." (PMID 35637970, 2022). "STAT3 activation via the OSM–OSMR interaction increases EMT, sphere-forming capacity, and tumor invasiveness, but how the OSM-STAT3 signaling pathway regulates a distinct transcriptional program is still unclear." (PMID 36551576, 2022). "This may be attributed to the increased tumor burden in advanced stages, or to the pathogenetic role of these molecules in disease progression, as, in two studies using cell lines, the activity of STAT5/BIC/miR-155 and JAK/STAT3/STAT4/miR-146a pathways was associated with disease progression." (PMID 36613718, 2022). "In conclusion, in LUAD cells, highly expressed mPRα enhances the activation of cAMP/JAK/STAT3 signaling and increases HIF1α-induced VEGF secretion into the tumor microenvironment, promoting HUVEC migration and tube formation under hypoxia." (PMID 35123491, 2022). "Our results demonstrate that STAT3 overexpression increased STAT3 and nuclear YAP IHC staining and protein expression in H146 mouse xenograft tumor tissue." (PMID 35885009, 2022). "This showed that the tumor suppression ability of siglec-15 silencing was counteracted by STAT1 overexpression and STAT3 overexpression." (PMID 35769818, 2022). "It has been reported that the interplay between B cells and ECs via the signal transducer and activator of transcription 3 (STAT3), an established and critical mediator of tumor angiogenesis." (PMID 35759090, 2022). "The protumoral activity derived from MDSCs is driven by several molecules present in the tumor as the macrophage migration inhibitory factor, B7 homolog 3 protein, also known as CD276, or signal transducer and activator of transcription 3 (STAT3)." (PMID 36338755, 2022). "CRC cells grown in culture exhibit decreased STAT3 signaling compared to primary tumors, and growing HT29 cells as a xenograft tumor reactivates this signaling." (PMID 36253360, 2022). "Significantly, targeting STAT3 induced anti‐HCC immune memory and accumulation of the important antitumour effector CD8+ T cells in tumour tissues, which expressed low levels of checkpoint molecules such as LAG‐3 and PD‐1." (PMID 35665592, 2022). "Both STAT3 and MYC expression are described as being involved in tumor formation, cancer metabolism and even metastasis." (PMID 36555426, 2022). "Another small-molecule STAT3 inhibitor, ODZ10117, also decreased the stem cell properties of GSCs and reduced tumor growth in vivo by targeting the SH2 domain of STAT3." (PMID 35740330, 2022). "Remarkably, EC patients had higher levels of known oncogenes (including STAT3 and EZH2) and lower levels of the known tumor suppressor lncRNA MEG3 when compared to normal samples." (PMID 35712514, 2022). "This formation is mediated predominantly by IFNγ-activated T cells, which subsequently induce phosphorylation of the transcription factors signal transducer and activator of transcription 3 (STAT3) and early growth response-1 (EGR-1) in tumor cells." (PMID 36124553, 2022). "HCC (N = 124) and CCA (N = 138) tumor tissue microarrays were stained for STAT1 and STAT3 using immunohistochemistry." (PMID 35267462, 2022).
tumor (continued). "In agreement with previous reports that indicate the importance of pSTAT3 and pSRC in PDAC, IHC-IF staining showed both elevated activated STAT3 and SRC in tumor cells of human PDAC cancer tissues." (PMID 36324587, 2022). "In conclusion, we demonstrated that in LUAD cells, highly expressed mPRα enhances the activation of cAMP/JAK/STAT3 signaling and increases HIF1α-induced VEGF secretion into the tumor microenvironment, promoting HUVEC migration and tube formation under hypoxia." (PMID 35123491, 2022). "STAT3 is highly phosphorylated in many cell types in the TME, including Treg cells, myeloid-derived cells and tumor cells." (PMID 34875483, 2022). "In summary, our results demonstrate that targeting STAT3 with LLL12B induces apoptosis, inhibits colony formation and cell migration in vitro, and suppresses tumor growth of TNBC cells in vivo." (PMID 36009550, 2022). "AKT, Raf/ERK, and STAT3 are downstream signaling factors of EGFR-mediated signaling and known to activate tumor growth and metastasis." (PMID 35572726, 2022). "Studies have shown that both histiocytes (e.g., macrophages and epithelial cells) and tumour cells promote PD‐L1 expression through the activation of JAK and STAT3 in response to proinflammatory factors." (PMID 35384279, 2022). "The differential analysis in normal breast tissue and tumor tissue revealed that, except for RIPK1, RIPK3, TNF, MAP3K7, and STAT3, all the other genes showed significantly differential expression in BRCA." (PMID 35686108, 2022). "In yet another Panc-1 study in which CuB (at 0.5–1.0 mg/kg) reduced tumor volume when cells in Matrigel were grafted into nude mice, alterations in JAK-STAT signaling (i.e., reduced levels of p-STAT3 and p-JAK2) were also noted." (PMID 36355554, 2022). "We therefore focused on Y705 phosphorylation (hereafter referred to as p-STAT3) and its role in ROBO3-mediated tumor progression." (PMID 35993361, 2022). "The interaction between nicotine and its receptor induces the activation of the JAK/STAT3 pathway, leading to the release of IGF-1 and CCL20 from M2 microglia cells that further stimulate tumor cell growth and cancer cell stemness." (PMID 35884845, 2022). "PKM2 enzyme also increases the activity of STAT3 and HIF-1α and their downstream factors/genes promoting angiogenesis and tumor growth." (PMID 36419156, 2022). "We further show that IGFBP2 augments IDO expression through the STAT3 signaling pathway in PDAC, thereby inducing Treg differentiation and tumor growth." (PMID 36556226, 2022). "We found markedly reduced SOCS1 levels accompanied by increased p-STAT1 and STAT1, decreased p-STAT3, and thus an increased p-STAT1/p-STAT3 ratio in miR-155–overexpressing EO771, 4T1, and AT-3 tumor cells compared with control cells." (PMID 35925680, 2022). "STAT3 is one of the major mediators of tumor-induced immunosuppression and was activated in MES-like state tumor cells, and NFKB1, an inflammatory regulon, was also upregulated in MES-like cells." (PMID 35669791, 2022). "Constitutive phosphorylation of STAT1, STAT3, and STAT5 has been detected in many tumor cell models." (PMID 35401182, 2022). "In addition, loss of CAF STAT3 led to an increase in CD8+ T cells and decrease in Foxp3+ Tregs in tumor lesions, which may be a consequence of the decreased number of M2 macrophages, or alternatively indicate direct communication between CAFs and T-cell subsets." (PMID 35803738, 2022). "The complex of PD-L1 and phosphorylated STAT3 can mediate the expression of GSDMC and then induce tumor cell pyroptosis." (PMID 36605437, 2022). "Then, we extracted the proteins from subcutaneously transplanted tumours and conducted western blotting experiments, which also confirmed reduced FOXM1, STAT3, p-STAT3 and GPX4 expression in subcutaneous tumours from the TST treatment group." (PMID 35859150, 2022).